AFP (alpha fetoprotein)
Diseases named in the same sentence as AFP in open-access papers (continued):
Sharing a sentence is not in itself a finding about the gene and the disease.
tumor (continued). "AFP was first proposed as a tumor marker for HCC in the 1960s and has since been widely used for clinical HCC detection." (PMID 36241994, 2022). "PIVKA-II was also reported as a prognosis marker in patients with HCC, as PIVKA-II and AFP have a positive correlation with the tumor burden." (PMID 35271670, 2022). "In the multivariate analysis, intrahepatic tumor volume (<50% vs. ≥50%: HR 16.7; 95% CI 1.71–163; p = 0.016), and AFP (<400 vs. ≥400: HR 3.38; 95% CI 0.84–19.7; p = 0.031) remained independent prognostic factors for OS." (PMID 35302279, 2022). "This study aims to assess the correlation between serum levels of alpha-fetoprotein and tumour dimensions in HCC patients, that were previously treated with DAAs for hepatitis C viral infection, obtaining sustained virologic response (SVR)." (PMID 35497085, 2022). "Alpha-fetoprotein (AFP) is considered a reliable tumor biomarker that is widely used for screening, diagnosing, and monitoring tumor recurrence and metastasis of HCC in daily clinical practice." (PMID 35626229, 2022). "A more aggressive tumor behavior, including a larger tumor size and a higher serum AFP concentration, is demonstrated in HCC patients with a low preoperative LMR when compared with in patients presenting a high preoperative LMR." (PMID 36612251, 2022). "Independent prognostic factors associated with OS identified in previous studies were albumin, alpha-fetoprotein, alkaline phosphatase and tumour size <5 cm." (PMID 36593888, 2022). "Compared with the ZNF334 high expression group, the proportion of people with high serum AFP( > 400 ng/ml), tumor number and portal vein tumor thrombus was greater, while the proportion of people with tumor capsule was lower." (PMID 35534462, 2022). "Following imaging, organs were harvested, and 18F activity was measured in major organs Animals treated with CpGf-AFP-NPs showed significant and specific activity in tumor tissue." (PMID 35857843, 2022). "Patients who underwent conversion therapy had higher serum albumin levels and a trend toward a smaller main tumor size, SN type, and lower serum AFP levels." (PMID 36291850, 2022). "The tumour sizes and serum levels of AFP, CEA and CA19-9 were compared between the proliferative and normal-like subtypes." (PMID 36345011, 2022). "Serum AFP has been widely used as a predictive biomarker for HCC and is generally associated with tumor size." (PMID 36161213, 2022). "The prognosis of HCC depends on various clinicopathological parameters, including serum alpha-fetoprotein (AFP) level, tumor size and focality, lymphovascular invasion (LVI), pathological stage and grade, and the background liver." (PMID 36117166, 2022). "Recently, the important role of biomarkers in liver transplantation has been recognized with high AFP (>1000 ng/mL) used as a surrogate for aggressive tumor biology and disqualifying patients for MELD exception points." (PMID 36533190, 2022). "MC-out patients with partial response or stable disease can undergo LT when tumor burden is within the up-to-seven criteria and serum AFP is <100 ng/ml." (PMID 35529597, 2022). "The nomogram C-index value (0.726) for OS was higher than that for IL-25 (0.559), HBV-DNA (0.569), AFP (0.584), encapsulation of tumor (0.591), and diameter of tumor (0.635) (all p < 0.05)." (PMID 36119529, 2022). "Compared with AFP, ctDNA was a more sensitive and accurate tumor marker, which can be used to monitor tumor burden and predict patient prognosis." (PMID 34543520, 2022). "Among them, serum alpha-fetoprotein (AFP) is a recognized indicator in the diagnosis and prognosis of HCC and associated with worse tumor phenotype and invasion in HCC." (PMID 36605430, 2022). "High AFP level, multiple primary tumors, and large tumor size, which represents the aggressiveness of the primary tumor, were related to increased early IHR." (PMID 35565210, 2022).
tumor (continued). "The decreased expression was also correlated with serum AFP levels, vein invasion, and progression of the tumor, nodes, and metastasis." (PMID 35804809, 2022). "Herein, we demonstrated that tumor size, tumor number, histological grade, and AFP were markedly related to MVI occurrence." (PMID 36684226, 2022). "In univariate regression analysis in the training group, AFP level, tumor capsule, tumor margin, and Edmondson grade showed significant differences between the high and low Ki-67 groups (P <0.05)." (PMID 35875154, 2022). "On univariate analysis, factors contributing to OS included PS, mALBI grade, up to seven criteria, relative tumor volume, serum alpha-fetoprotein (AFP) value before lenvatinib initiation, tumor morphology, and history of systemic therapy." (PMID 36291850, 2022). "Patients are divided according to their albumin, bilirubin, AFP levels, and the size of dominant tumor." (PMID 35330436, 2022). "AFP is the most classical tumor marker, and 400 ng/mL is often used as the cutoff value in patients with nonruptured HCC." (PMID 35342424, 2022). "Through comparison between the low SV and the high SV groups, we found that most tumor-related variables (tumor size, AFP, MVI, BCLC staging, and tumor differentiation) didn’t add a contribution to late recurrence." (PMID 35686100, 2022). "Once the tumor has progressed after treatment, more AFP will be produced, and the serum AFP levels will be elevated." (PMID 36686731, 2022). "Among the HCC marker genes, a higher percentage of tumours showed GPC3 expression compared to AFP expression [73% (23/30) vs. 43% (13/30)]." (PMID 36345011, 2022). "All patients received the detection of tumor markers, at least hCG and AFP, in serum, and three of them synchronously received the CSF test." (PMID 35378836, 2022). "In a small Spanish study, a significant correlation was found between tumour size and extent of elevations of bHCG and AFP." (PMID 36358866, 2022). "After this entry selection, the clinical course during downstaging procedures concerning the tumor and the AFP response is of paramount importance and serves as an additional final selection tool." (PMID 35529597, 2022). "Sorafenib was preferred in patients > 60 years of age, AFP ≤ 200 ng/mL, and tumor size ≤ 5 cm for OS." (PMID 35337274, 2022). "In this AFP model, patients with one to three tumours, the largest of which has a diameter of 6 cm, or up to four lesions with a maximal diameter of 3 cm, are considered for LT if their AFP level is a maximum of 100 ng/mL." (PMID 35740638, 2022). "The overexpression of HOXA13 was correlated with the grade, size, microvascular invasion, capsular spread in the nodes, alpha-fetoprotein (AFP) level, and tumor-node-metastasis (TNM) staging in HCC." (PMID 34617205, 2022). "Univariate and multivariate Cox analysis found that numerous factors significantly affected CSS, including sex, race, marital status, AFP level, grade, T stage, tumor size, surgery, and chemotherapy." (PMID 35296046, 2022). "Tumor markers such as alpha-fetoprotein (AFP), tumor-specific growth factor (TSGF), and Golgi protein 73 (GP73) are commonly used for tumor diagnosis." (PMID 35711497, 2022). "The RETREAT score, reported in 2018, also predicts the recurrence rate using the MVI from postoperative histopathological examinations in combination with the maximum tumor diameter, number of tumors, and AFP level." (PMID 35053580, 2022). "Downregulation of ABAT expression was correlated with patient age, tumor T stage classification, pathological stage, histologic grade, and AFP level of HCC and was an independent prognostic factor for HCC." (PMID 35847853, 2022). "Tumor markers such as alpha-fetoprotein (AFP), carbohydrate antigen 19-9 (CA19-9), and carcinoembryonic antigen (CEA) were negative." (PMID 36034453, 2022).
tumor (continued). "With this score model, the tumor diameter and neutrophil-to-lymphocyte ratio, as well as the AFP level, were selected as preoperative determinants for the pre-MORAL score." (PMID 35053580, 2022). "The following situations related to AFP seem to be important in oncological practice: elevated levels at the time of diagnosis, changes in levels during and after anti-neoplasm treatment and increasing AFP in specific clinical situations." (PMID 35204369, 2022). "Blood tumor markers including carbohydrate antigen-125 (CA-125) and alpha-fetoprotein (AFP) were in the normal range." (PMID 35761185, 2022). "They listed one or less viable tumors on imaging, viable tumor diameter of ≤1 cm, and AFP ≤20 ng/mL as independent predictors for successful pathological downstaging." (PMID 35053558, 2022). "In HCC tissues, IQGAP1 expression is positively correlated with tumor size, number, stage, and HBV surface antigen (HBsAg) and alpha-fetoprotein (AFP) expression but inversely correlated with tumor differentiation." (PMID 35785216, 2022). "This study supported the current placement of upper limits on tumor burden amenable to downsizing but perhaps more importantly also suggested further evaluation of AFP’s role in prognosticating post-transplant outcomes in down staged patients." (PMID 36290870, 2022). "Tumor size and operation were the most important factors influencing patient survival, followed by histological tumor grade, AFP, and T stage." (PMID 35296046, 2022). "In order to better identify MVI preoperatively, other easily available clinical indicators, termed tumor size and AFP, were also incorporated." (PMID 35310437, 2022). "We found that high expression of STMN1 was related to the age, weight, AFP level, tumor status, pathological stage, and histological grade of HCC patients." (PMID 36127700, 2022). "Tumor margin, direct bilirubin, maximum tumor diameter, and AFP integrated into the nomogram model were confirmed as independent predictors of MVI risk." (PMID 36577952, 2022). "Features associated with an increased risk of both OS and DFS were HBV, AFP serum level, ALBI score, tumor stage, tumor size and the state of TLS, except that Capsular (HR = 0.53, p = 0.03) was the protect factor for OS in Univariate Cox regression analysis." (PMID 36082777, 2022). "Before PSM, low-dose dopamine use was associated with a higher grade of ASA physical status (p = 0.036), larger tumor size (p = 0.032), lower AFP level (p = 0.015) and lower ALT level (p = 0.008)." (PMID 36091153, 2022). "Old age, male gender, elevated alpha-fetoprotein level, tumor size, and background liver were important prognostic parameters." (PMID 36117166, 2022). "The tumor markers AFP and beta-HCG were within normal values; thus, a “watch and wait” approach was decided upon." (PMID 36556917, 2022). "HbsAg, tumor number, HVTT, metastasis, AFP, and ALBI were independent risk factors for OS, and tumor number, PVTT, HVTT, and metastasis were independent risk factors for PFS." (PMID 36310160, 2022). "An “early TGF-β signature” has been described, characterized by lower tumor stage, reduced serum AFP, and improved patient survival, indicative of tumor suppression by TGF-β." (PMID 36467404, 2022). "A nomogram was then developed based on inflammatory score, AFP, and tumor size for patients with HCC to identify MVI before surgery." (PMID 35310437, 2022). "In the second study of 130 patients, aged 4 to 44 years, a preoperative increase in at least one of the tumor markers (AFP, β-hCG, LDH) was the only factor significantly affecting progression-free survival." (PMID 35204369, 2022). "High expression of POGK significantly correlated with tumor status (p = 0.036), race (p = 0.025), weight (p = 0.002), body mass index (BMI, p = 0.033), histologic grade (p < 0.001), and alpha-fetoprotein (AFP, p < 0.001)." (PMID 36421335, 2022).
tumor (continued). "Other factors, such as the BCLC stage, extrahepatic spread, baseline tumor marker (AFP/DCP) levels, ALBI grade, and FIB-4 index need to be considered in the management of patients with HCV-related HCC." (PMID 36230773, 2022). "Initial diagnosis of such neoplasms and further monitoring of therapeutic response is achieved through several imaging modalities, along with serum biomarkers such as alpha-fetoprotein (AFP)." (PMID 36551606, 2022). "AFP is a well-known tumor marker and is widely used in the management of HCC, such as in surveillance, diagnosis, monitoring of treatment response, and prognosis." (PMID 36358711, 2022). "The new tumour marker M371 is much more frequently expressed than the classical markers bHCG and AFP." (PMID 36358866, 2022). "It seems that lenvatinib is effective against more aggressive tumors (AFP > 200 ng/mL and tumor size > 5 cm), and post-sorafenib treatment is effective with a lower tumor burden (AFP ≤ 200 ng/mL and tumor size ≤ 5 cm)." (PMID 35337274, 2022). "Correlation analysis using data from the patients treated at our center showed that serum AFP level (p < .0001), vascular invasion (p = .0367), tumor stage (p = .0267), and differentiation (p = .0138) were significantly associated with TMCO1-AS1 expression." (PMID 35141283, 2022). "The results showed that CSS, AFP level, tumor number, tumor size, and macrovascular invasion were independent risk factors of both RFS and OS." (PMID 35637856, 2022). "Several studies have reported that baseline or follow-up AFP levels are correlated with survival and/or tumor recurrence." (PMID 35401038, 2022). "On the other hand, studies have also demonstrated an independent prognostic value of AFP on OS after resection, as well as a correlation with tumour size and number." (PMID 36233670, 2022). "Up to date, there are only limited blood tumor biomarkers available, including alpha-fetoprotein (AFP), cancer antigen 19-9 (CA19-9), and carcinoembryonic antigen (CEA), whose sensitivities remain far from satisfactory." (PMID 35105875, 2022). "Among tumor- and pten-related genes, alpha-fetoprotein and PPARγ genes were reduced by probiotics treatment." (PMID 36171333, 2022). "A gradual increase in the tumor-related serum marker AFP was observed beginning in week 12, and its serum levels were significantly higher than those in the normal control and normal-ART groups (all P < 0.01)." (PMID 36123535, 2022). "Present in 60–80% of patients, circulating serum AFP levels have demonstrated clinical utility, as it corresponds with tumor expression and growth." (PMID 36290870, 2022). "Univariate analysis of the clinical parameters showed that marital status, grade, AFP level, vascular invasion, tumor size, number of lesions, and T stage were related to the 5-year CSD of patients." (PMID 36451200, 2022). "Carcinoembryonic antigens are the third important TAA tumor antigens, such as alpha fetoprotein (AFP) and carcinoembryonic antigen (CEA)." (PMID 36341370, 2022). "In the correlation analysis with clinicopathological features, F9 was significantly correlated with T stage, TNM stage, histological grade, vascular invasion, tumor status, AFP, and PT." (PMID 36685860, 2022). "The National Academy of Clinical Biochemistry, which is more specialized in tumor marker status recommends only considering AFP and hCG levels that have been extensively studied and validated by independent teams." (PMID 36140449, 2022). "In contrast, maximum tumor diameter (P = 0.001), AFP level (P = 0.006), PIVKA-II level (P = 0.026), tumor-adjacent tissue hardness (P = 0.001), and SR (P = 0.023) were significantly different between the patients with and without MVI." (PMID 35562688, 2022). "The RFS nomogram C-index value (0.645) was higher than that for HBV DNA (0.542), AFP (0.564), tumor count (0.538), encapsulation of tumor (0.561), IL-25 (0.549), tumor diameter (0.582), and microvascular invasion (0.559) (all p < 0.001)." (PMID 36119529, 2022).
tumor (continued). "In our center, patients with HCC recurrence had significantly higher AFP concentration, larger tumor size, vascular invasion, and poorer tumor pathological stage." (PMID 35936699, 2022). "For HCC tumours less than 5 cm in size, AFP has a sensitivity between 49% and 71% and a specificity between 49% and 86%." (PMID 36013482, 2022). "AFP levels have also been recommended as a predictor for a successful pre-transplant tumour size reduction, to which further investigation is essential." (PMID 36291898, 2022). "Two vertical lines were drawn at lambda.min and lambda.1se to screen for 10 predictors with non-zero coefficients, including sDR5 level, WBC, TBIL, ALP, GGT, ascites, AFP level, tumor number, Child-Pugh stage, and BCLC stage." (PMID 36605430, 2022). "Baseline sCTLA‐4 level had better sensitivity, specificity, PPV, and NPV than AFP for predicting of early tumor recurrence." (PMID 35435327, 2022). "AFP tumor biomarker or AST/ALT metabolism makers at baseline or 12 months of treatment were not independent factors of liver related mortality or liver transplantation." (PMID 36291847, 2022). "Our data showed that preoperative CTC-NLR score correlated with AFP, tumor size, tumor number, BCLC stage, and PVTT." (PMID 35880030, 2022). "The two tumor markers (AFP and CA199) are the most commonly used cancer biomarkers to distinguish ICC and HCC." (PMID 35480111, 2022). "As a new class of vaccines for tumor immunotherapy, DEXs, such as AFP-enriched DEXs, induce a strong immune response with antigen specificity." (PMID 35185900, 2022). "The logistic regression analysis showed that EXO1 expression levels were associated with the clinical stages including T stages and histological stages, tumor status, and AFP levels." (PMID 35769911, 2022). "Univariate analysis showed that ALG3 expression, histology classification, TNM stage (AJCC), tumor size, tumor number, vascular tumor emboli, serum AFP, and HBsAg were the potential independent prognostic factors for HCC patients." (PMID 35782861, 2022). "Elevated tumor biomarker level, including AFP, CEA, PSA, and CA125, is usually associated with either higher tumor burden or increased malignancy and thus the intuitively higher prevalence of sLM and poorer survival." (PMID 35406378, 2022). "Based on TCGA cohorts, our results suggested that many TRIMs were related to distinct clinical parameters, including age, fibrosis, gender, AFP levels, neoplasm histologic grades, and vascular invasion." (PMID 35873464, 2022). "Our study found that the serum sDR5 level, white blood cell count, presence of ascites, AFP level, and tumor number ≥ 3 were independent prognostic factors for HBV-HCC patients." (PMID 36605430, 2022). "Accordingly, the Metroticket 2.0 criteria have been modified for patients with progressive disease during downstaging, where tumor criteria have been reduced by 1–2 cm in all AFP categories." (PMID 35529597, 2022). "In the clinicoradiological factors, gender, alpha-fetoprotein (AFP) level, tumor shape and halo sign served as the independent risk factors of MVI, with which the area under the curve (AUC) is 0.802." (PMID 36387156, 2022). "For instance, by infecting a mouse DC cell line with lentiviruses encoding the α-fetoprotein (AFP) gene, DC-derived exosomes expressing AFP induced a robust immune response in vivo that led to suppressed tumor growth and prolonged animal survival." (PMID 36119094, 2022). "We analyzed the correlation between up-regulated DEGs and the T stage, pathologic stage, histological grade, AFP, vascular invasion, tumor status, PT, and race." (PMID 36685860, 2022). "The resulting five variables in the final model, including AFP, tumor size, bilirubin, INR, and ascites, represent the most predictive risk factors in this population." (PMID 35029055, 2022). "Serum inflammatory markers were normal, as were tumor markers, such as AFP, carcinoembryonic antigen, and cancer antigen 19-9." (PMID 36197224, 2022).